HSPG2 (heparan sulfate proteoglycan 2)
Diseases named in the same sentence as HSPG2 in open-access papers (continued):
Sharing a sentence is not in itself a finding about the gene and the disease.
pulmonary fibrosis (1 paper, 2022). Chronic progressive interstitial lung disorder characterized by the replacement of the lung tissue by connective tissue, leading to progressive dyspnea, respiratory failure, or right heart failure. "Using primary human lung cells, we show that SARS‐CoV‐2, and to a lesser degree SARS‐CoV, perturbs abundance of pulmonary fibrosis‐related proteins such as SERPINE1/PAI1, FN1, and HSPG2." (PMID 35833542, 2022).
scleroderma (1 paper, 2023). Scleroderma is a rare autoimmune connective tissue disorder characterized by abnormal hardening of the skin and, sometimes, other organs. "Perlecan (HSPG2) was elevated in scleroderma ECs compared to the controls and the perivascular regions stained robustly for HSPG2." (PMID 37443817, 2023). "Genes associated with ECM components, such as COL4A1, heparan sulfate proteoglycan 2 (HSPG2), and actin beta (ACTB), as well as phospholipase C gamma 2 (PLCG2), fatty binding protein 4 (FABP4), and galectin 1 (LGALS1), also showed higher expression levels in scleroderma." (PMID 37443817, 2023).
urothelial carcinoma (1 paper, 2023). A malignant neoplasm derived from the transitional epithelium of the urinary tract (urinary bladder, ureter, urethra, or renal pelvis). "HSPG2 showed high staining in the cytoplasm and nucleus of normal bladder cells, but no staining was detected in urothelial carcinoma cells." (PMID 36911676, 2023).
ZIKV infection (1 paper, 2019). "HSPG2 and ICAM-1 mRNA expression increased during culture of hSCs, but this was not affected by ZIKV infection." (PMID 31289325, 2019).
tumor (64 papers, 2013 to 2026). "In contrast, tumor-associated ECs predominantly expressed pro-angiogenic and extracellular matrix remodeling genes, including Heparan Sulfate Proteoglycan 2 (HSPG2) and Periostin (POSTN)." (PMID 40599812, 2025). "In this study, we comprehensively integrated the pretreatment somatic mutational profiles and clinical information of both tumors and observed that HSPG2 mutations were associated with favorable tumor immunogenicity and immunotherapeutic efficacy." (PMID 35884556, 2022). "C0 corresponded to tumor-associated [heparan sulfate proteoglycan 2 (HPSG2) and plasmalemmal vesicle-associated protein (PLVAP)] and C1 ECs were blood ECs (FLT)." (PMID 34900703, 2021). "Instead, HSPG2 is associated with tumor progression and poor cancer prognosis." (PMID 37854606, 2023). "While shRNA to Hspg2 barely affected neutrophil cytotoxicity, shRNA to Nidogen-1 reduced tumor cell susceptibility to neutrophil cytotoxicity, suggesting that Nidogen-1 contributes to the neutrophil recognition of tumor cells required for the subsequent cytotoxic effect." (PMID 35453656, 2022). "Moreover, Nidogen-1 was found to bind tumor cell-associated Hspg2, suggesting that these components form complexes on the cell surface." (PMID 35453656, 2022). "HSPG2 deficient mice showed impaired angiogenesis, delayed wound healing and tumor growth." (PMID 23593148, 2013). "Proteoglycan HSPG2 is one of the classic members of several types of tumor ECM and promotes tumor growth by various means." (PMID 40756366, 2025). "EC5 displayed high expression levels of genes related to ECM remodeling (COL4A1,COL4A2,HSPG2,MMP2,SPARC),which have been previously implicated in tumor angiogenesis." (PMID 41394809, 2025). "Simultaneously, increased NOTCH4 and HSPG2 signals were detected, which contribute to tumour vascular structure formation." (PMID 38778448, 2024). "Others such as EMILIN1 and HSPG2 were expressed in both tumor and adjacent normal tissue and, thus, unsuitable for selective targeting of malignant tissue." (PMID 37098922, 2023). "The intact form of this protein was found increased in tumor prostate tissue, but in sera from PCa patients raised levels of HSPG2-derived fragments resulting from matrix metalloproteinase 7 (MMP7) degradation were observed." (PMID 35454907, 2022). "In this study, for the first time, we demonstrated that TNBC tissue exhibits a distinctive stromal deposition of HSPG2 in high cell density areas and surrounding tumor islands where TAMs are highly infiltrated, mimicking a physical shield." (PMID 35887248, 2022). "Since Hspg2 is also expressed on the surface of the tumor cells, and Nidogen-1 interacts with Hspg2, it is likely that Nidogen-1 binds to tumor cell surface through Hspg2." (PMID 35453656, 2022). "Proteoglycans such as HSPG2 (perlecan), lumican and biglycan were identified in tumor ECM, although their abundance was similar to that in healthy cortex." (PMID 36077607, 2022). "To study the involvement of tumor expressed Nidogen-1 in neutrophil cytotoxicity, we used specific shRNA to knock down the expression of Nidogen-1 and Hspg2 in AT3 and LLC cells." (PMID 35453656, 2022). "We further show that Nidogen-1 binds to the surface of tumor cells through the G2-domain which is known to be the binding domain of Nidogen-1 to Hspg2." (PMID 35453656, 2022). "RAGE is one of the receptors on the tumor cells that assist keeping Nidogen-1 and Hspg2 on the tumor cell membrane." (PMID 35453656, 2022). "We further observed that the CLRs interact with tumor Nidogen-1 and Hspg2, two sulfated glycoproteins of the basement membrane." (PMID 35453656, 2022). "Using mouse models of cancer, we have presented data showing that the two CRLs Dectin-1 and Clec4e on neutrophils are co-operating in recognizing Nidogen-1 and Hspg2 on the tumor cell surface." (PMID 35453656, 2022).
tumor (continued). "ITGA2 interacted with COL1A1, COL1A2, COL8A1, FN1, and HSPG2, mediating the tumor cell–fibroblast and tumor cell–endothelial cell connection." (PMID 35719923, 2022). "In a recent TNBC study, an anti-HSPG2 antibody successfully inhibited tumor growth in a mouse xenograft model, highlighting the promising role of HSPG2 as a therapeutic target in tumor cells." (PMID 35887248, 2022). "HSPG2 is represented in the stroma of several tumor types, where it is predicted to bind tenascin C and modify growth factor signaling, including VEGF and FGF, by increasing the binding of these ligands to their receptors." (PMID 36077607, 2022). "Tumor endothelial cells were mainly represented by clusters 2 and 4, and showed high expression of angiogenesis markers such as VWA1 and HSPG2, as well as INSR, encoding an endothelial marker protein and possible therapeutic target (arrowheads)." (PMID 34663877, 2021). "Quantification of staining revealed that HSPG2 expression increased with advancing tumor stage, with the highest expression being observed at metastatic sites." (PMID 31462656, 2019). "Identification of HSPG2 as a unique tumor cell antigen and the development of a fully human antibody demonstrating therapeutic efficacy represent a potential new point of focus in TNBC." (PMID 31462656, 2019). "We investigated the expression of HSPG2 in human TNBC and the ability of anti-HSPG2 antibodies to specifically target and inhibit tumor growth in a mouse xenograft model." (PMID 31462656, 2019). "Perlecan/heparan sulfate proteoglycan 2 (HSPG2) is an extracellular proteoglycan that orchestrates tumor angiogenesis, proliferation, differentiation and invasion." (PMID 29740048, 2018). "HSPG2 is also required for metastasis and leads to efficient tumor growth and enhancing angiogenesis." (PMID 23593148, 2013). "Knockdown of perlecan/HSPG2 sensitized radioresistant DU145 RR cells to irradiation while the sensitivity of DU145 parental cells did not change, indicating a potential role for perlecan/HSPG2 and its associated proteins in suppressing tumor radioresistance." (PMID 39149513, 2024). "The knockdown of Nidogen-1, but not that of Hspg2, led to reduced susceptibility of the tumor cells to neutrophil cytotoxicity." (PMID 35453656, 2022). "Both Nidogen-1 and Hspg2 were found to be expressed on the tumor cell surface." (PMID 35453656, 2022). "Knockdown of Nidogen-1, but not of Hspg2, in tumor cells reduced their susceptibility to neutrophil cytotoxicity, suggesting that Clec4e/Dectin-1 contribute to the recognition of tumor cells through interaction with Nidogen-1." (PMID 35453656, 2022). "Notably, the Nidogen-1/Hspg2 complexes also interact with tumor RAGE, suggesting that these extracellular matrix molecules strengthen the neutrophil-tumor cell synapse by bridging CLRs with RAGE." (PMID 35453656, 2022). "In addition, perlecan/HSPG2, a heparan sulfate proteoglycan, gathered in the tumor marginal stromal, was considered a molecular switch of angiogenesis in TME." (PMID 35784750, 2022). "To assert SULF1 functions as a tumor suppressor, we considered not only its direct impact in our 3D tricultures but also its expression levels by cell lines and metastatic tissues, in addition to the influence of tumor-associated cells regulating SULF1 and HSPG2 expression." (PMID 32413029, 2020). "Also, while HSPG2 mRNA was mostly expressed by CAFs, close to 20% of E-cad+ tumor cells were HSPG2+." (PMID 32413029, 2020).
tumor (continued). "According to the marker genes, these clusters were designated as blood endothelial cells (FLT1; clusters 0–3, 5, 6), lymphatic endothelial cells (PDPN: cluster 4), tumor endothelial cells (HSPG2: clusters 0 and 2–6), and normal endothelial cells (MT2A; clusters 0–6)." (PMID 33083004, 2020). "Additionally, it was shown that the MUC1 SEA domain originates from heparin sulphate proteoglycan of basement membrane (HSPG2; perlecan), an inducer of tumour cell growth." (PMID 30875782, 2019). "Therefore, ADCY8 and HSPG2 were selected as the most promising candidates from this double germline–tumor disrupting SNV approach." (PMID 30871259, 2019). "Interestingly, it has been previously reported that an increase in matrix metalloproteinase enzymes in the tumor stroma leads to a reduction of HSPG2 expression in the ECM, thus favoring cell dispersion and invasiveness." (PMID 31462656, 2019). "HSPG2 proteoglycan interacts with extracellular matrix components and is often overexpressed in different types of cancers, including CRC, that could be associated with tumor growth and invasion." (PMID 37241967, 2023). "shRNA to Nidogen-1, but not shRNA to Hspg2, caused significant reduction in the sensitivity of tumor cells to neutrophil-mediated cytotoxicity, suggesting a role for Nidogen-1 in neutrophil recognition of tumor cells." (PMID 35453656, 2022). "Furthermore, the correct differentiation of M2 associated with a stiffer matrix significantly modulated the expression of genes of the NF-κB pathway, confirming the involvement of heterodimeric p65/p52 complex in the transcriptional regulation of HSPG2 and in a tumor immune-escaping process." (PMID 35887248, 2022). "Interestingly, the Nidogen-1/Hspg2 complex was also found to interact with tumor RAGE." (PMID 35453656, 2022). "Substantiating this premise, EC4 subclass analysis identified conserved functional modules including ECM remodeling effectors (HSPG2,MGP,POSTN) and tumor niche-modifying factors (RAMP2,ACKR1,CD74)." (PMID 41394809, 2025). "Of note, we confirmed a correlation between the expression levels of perlecan/HSPG2 and LAMB3 or HSPG2 and SRPX and found that it increases during tumor progression." (PMID 39149513, 2024). "Inhibition of HSPG2 leads to significant tumor shrinkage and inhibition of angiogenesis in human CRC tumor xenografts." (PMID 37241967, 2023). "We obtained five cell subpopulations, including four clusters (C0, C1, C2, C4) of tumor endothelial cells (PLVAP, VWA1, HSPG2, and INSR) and lymphatic endothelial cells (C3) (PDPN, CCL21)." (PMID 37715019, 2023). "It has been demonstrated that EGR1 can regulate angiogenesis to promote tumour cell invasion, which is upregulated in the EMT process and regulates the target gene HSPG2 to promote EMT." (PMID 37817210, 2023). "The scRNA-seq data showed that ITGA2 was mainly expressed in tumor cells, while its ligands COL1A1, COL1A2, COL8A1, FN1, and HSPG2 were expressed in fibroblasts and endothelial cells." (PMID 35719923, 2022). "Upregulation of HSPG2 and MYO1B in vasculature in the tumor core were validated by immunostaining in human specimens." (PMID 34228647, 2021). "HSPG2, also known as perlecan, is a heavily glycosylated protein component of the extra-cellular matrix (ECM) that plays essential roles in tumor vascularization, that is closely related to tumor growth and metastasis." (PMID 33182810, 2020). "Expression of both HSPG2 and SULF1 was concentrated in αSMA-rich stroma near PCa tumor nests, where infiltrating pro-tumor TAMs also were present." (PMID 32413029, 2020). "TNFα‐CSG treatment also reduced other tumour ECM components, which included fibrillar collagens (stained with picrosirius red), collagen I, perlecan (HSPG2) and fibronectin (Fig EV4B)." (PMID 31709774, 2019).
tumor (continued). "Components of the basement membranes were found to be expressed by the tumor cells only (laminin chains α3, β3, γ2), by both compartments (laminin chains α5, γ1, COL6A3, HSPG2) or by the stroma (Nidogens 1 and 2)." (PMID 24618895, 2014). "Indeed, a number of proteins within the PG score, such as LUM, HSPG2, DCN and BGN, have established tumor suppression functions in other cancer types." (PMID 38810090, 2024). "In addition, the CLR receptors Dectin-1 and Clec4e on neutrophils interact with Nidogen-1/Hspg2 expressed on the tumor cell surface, some of which also interact with the tumor RAGE, thus bridging the neutrophils to the tumor cells." (PMID 35453656, 2022). "Surprisingly, HSPG2 mRNA was significantly upregulated in macrophages exposed to TCM, suggesting that secretome released by tumor cells may contribute to exacerbating TAM activation and HSPG2 production." (PMID 35887248, 2022). "Notably, tumor ECs were featured by upregulation of angiogenesis-related genes including collagens (e.g., COL4A1, COL4A2), PXDN, SPARC and HSPG2, as well as proliferation markers (e.g., MKI67, TOP2A)." (PMID 36138435, 2022). "The finding that both tumor RAGE and CLRs interact with Hspg2/Nidogen-1, suggests that Hspg2/Nidogen-1 might bridge between RAGE and CLRs, and thus strengthen the neutrophil-tumor cell synapse." (PMID 35453656, 2022). "Genes encoding collagens (COL4A1, COL4A2), collagen-modifying enzyme (PXDN), and other components of the basement membrane (LAMB1, HSPG2) also ranked in the top 10 most enriched Co1 EC markers, indicating that extensive matrix remodeling occurs in GBM during tumor angiogenesis." (PMID 34228647, 2021). "Compared with patients with tumor size no more than 5 cm, the mutation percentages of ALB, FBN3, HSPG2, and FLG2 were increased in patients with tumor size more than 5 cm." (PMID 32017470, 2020). "Among mice immunized with HYLSSILRL or SYLLGSGEARL (derived from Hspg2), about 50% of the immunized mice were able to reject the tumor completely but the activity was not significant because of a high variation in tumor rejection." (PMID 31219806, 2019). "The importance of GAG decoration on perlecan has been further demonstrated in Hspg2Δ3/Δ3 mice, whereby deletion of exon 3 of the Hspg2 gene removes the GAG attachment sites in Domain I and the mice presented with impaired angiogenesis, delayed wound healing, and retarded tumor growth." (PMID 32010611, 2019). "Through public data and experimental verification, we found that inhibiting the expression of EGR1 can regulate the invasion of tumour cells, and the decreased expression of EGR1 significantly upregulated the expression of E-cadherin and downregulated the targeted genes FAS and HSPG2." (PMID 37817210, 2023). "Interestingly, co-immunoprecipitation studies show that sRAGE-Fc binds endogenous Hspg2 and Nidogen-1, suggesting that tumor RAGE may contribute to their binding to the tumor cell surface." (PMID 35453656, 2022). "We observed that in the tumor matrix, the expression of HSPG2 was increased in M2 macrophages co-assembled with MDA-MB-231 cells compared to M2 + MCF7 cells (1.72- vs. 0.34-fold, p = 0.0008), correlated with the deposition of HSPG2 by CD206+ macrophages in TNBC biopsies." (PMID 35887248, 2022). "On the other hand, in the healthy matrix, HSPG2 was increased in M2 macrophages but not in the presence of tumor cells (1.68- vs. 0.33-fold in M2 + MCF7 cells, p = 0.0037), suggesting that neoplastic cells and correct matrix stiffness are both required to induce HSPG2 expression." (PMID 35887248, 2022).